TLR9 (toll like receptor 9)
Diseases named in the same sentence as TLR9 in open-access papers (continued):
Sharing a sentence is not in itself a finding about the gene and the disease.
tumor (continued). "The reduced expression of TLR7 and TLR9 induced by the immunosuppressive tumor microenvironment in pDCs was also demonstrated in ovarian and breast cancers." (PMID 38504978, 2024). "Toll-like receptor 9 is responsible for activating innate immune cells and mediating the high expression of PD-L1/PD-L2 in fibroblasts, thus promoting tumor progression." (PMID 38605944, 2024). "Overall, these data further support the notion that CPG-1668-mediated TLR9 stimulation in immune cells limits RM1 tumor growth via the secretion of type I IFN, leading to reduced RM1 cell proliferation and that RM1 cells fail to directly respond to CPG-1668." (PMID 38201300, 2024). "Combining a TLR9 agonist (CpG) with a polyspecific integrin‐binding peptide (PIP) to generate a tumor‐targeting immunomodulator, referred to as PIP‐CpG, triggered tumor regression and prolonged the survival of mice with BC tumors." (PMID 38685971, 2024). "Activation of TLR9 signaling pathways can promote tumor cell proliferation, survival, and invasion by inducing the production of pro-inflammatory cytokines, chemokines, and growth factors." (PMID 38903515, 2024). "Activation of TLR-9 triggers a downstream intracellular signaling cascade that results in NFkB signaling that releases a type I IFN secretion in the tumor microenvironment." (PMID 36831449, 2023). "Tumor-specific murine CD8 T cells [derived from splenocytes of plem-1 T cell receptor (TCR) transgenic mice] were conditioned in vitro using TLR9 - activated B – cells." (PMID 36969196, 2023). "A trend of increasing TLR9 and IRF1 mRNA expression, associated with a pro-inflammatory, anti-tumor phenotype was observed in BMDMs treated with both RXR agonists." (PMID 36901727, 2023). "These phenotypic changes following CpG exposure were replicated in vitro, suggesting that CpG is acting directly on A20 cells via their confirmed TLR-9 to modify tumor cell phenotype." (PMID 37016127, 2023). "The role of TLR9 in tumor progression and response to treatment varies considerably in the literature." (PMID 37112730, 2023). "The potency of TLR9 agonists in enhancing the anti-tumor response has been reported in several preclinical studies since the early 2000s." (PMID 37365634, 2023). "Based on the preliminary data available, TLR7 and TLR9 agonists currently in development suggest anti-tumor activity when used as monotherapy or in combination with approved immune checkpoint inhibitors." (PMID 36890302, 2023). "This is consistent with previously published data demonstrating that TLR-9 activation increases the proportion of MDSC but inhibits their immunosuppressive role in tumor-bearing mice by inducing their maturation and differentiation." (PMID 38292484, 2023). "Several studies have demonstrated that TLR9 agonists can induce significant anti-tumor immunity by activating B cells." (PMID 37936697, 2023). "R848 (TLR7/8 agonist), and lefitolimod (TLR9 agonist) have been found to transform TAMs to M1 macrophages and limit tumor progression." (PMID 37720226, 2023). "Stimulators of interferon genes (STING) and toll-like receptor 9 (TLR9) agonists are considered promising candidates in several preclinical tumor models with the potential to be used in clinical settings." (PMID 37901237, 2023). "This shows that in hypoxic HCC cells, histone H3 activates TLR9, induces caspase-1 activation and subsequently produces a variety of inflammatory mediators, which in turn promotes tumor proliferation and metastasis." (PMID 37082731, 2023). "Toll-like receptor 9 (TLR-9) is a suitable potential option for achieving substantial immunological stimulation at the tumor location." (PMID 37469419, 2023). "In the context of tumor EV vaccines, we show that the conjugation of toll-like receptor 9 agonists onto EVs enables timely activation of dendritic cells and generation of superior antitumor CD8+ T cell response." (PMID 38052869, 2023).
tumor (continued). "LILRA4 and TLR9 were selected based on their well-delineated expression in multiplex fluorescence staining, using non-tumor tonsil tissue as a control." (PMID 37435086, 2023). "HMGB1 is responsible for the activation of tumor cells via the toll-like receptor 9 (TLR9)-pathway, which enhances proliferation, migration, and the invasive potential of cancer cells." (PMID 37444436, 2023). "Conversely, the down-regulation of Wnt2b/β-linked protein expression through the use of Toll-like receptor 9 (TLR9) agonist CpG ODN has been shown to inhibit M2-like TAM polarization and exert anti-tumor effects." (PMID 37968714, 2023). "The application of Toll-like receptor 9 (TLR9) agonist shows anti-tumor effect by driving the metabolic reprogramming in macrophages." (PMID 37740232, 2023). "In particular, significant correlations between TLR-9 expression levels and clinicopathological variables, such as histological grade and tumor–node–metastasis (TNM) stage, highlight the potential prognostic importance of TLR-9 in GC." (PMID 37894471, 2023). "As a result of STING and TLR9 signaling pathways and the production of type I and II IFNs, the cross-priming of tumor antigens by CD8+ T cells facilitates antitumor immune responses." (PMID 37901237, 2023). "For example, using a murine model of lymphoma, intratumoral injection with an IL-12-Fc fusion protein and TLR9 agonist (CpG) can lead to elimination of the injected primary tumor as well as a secondary tumor site." (PMID 37965337, 2023). "TLR9 activation has been shown to promote tumor regression directly through the action of TRAIL, and indirectly through the activation of NK cell-mediated tumor killing." (PMID 37112730, 2023). "We chose this transgenic mouse model for specifically studying the targeted approach of antibody-mediated delivery of TLR9 agonist to the tumor tissue and the induction of anti-tumor immunity as a consequence of local innate immune activation." (PMID 36913398, 2023). "In preclinical and clinical studies, TLR9 agonists used either as monotherapy or in combination therapy with immune checkpoint inhibitors showed anti-tumor responses." (PMID 35697801, 2022). "TLR4 and TLR7 were the most strongly correlated with tumour stemness features, but TLR9 had an undefined connection with the stemness index in various malignancies, and TLR4, TLR7, and TLR8 were the most associated with the tumour microenvironment." (PMID 35801728, 2022). "Mechanistically, the microbiome has been reported to affect tumor-specific CD8+ T cells via TLR4 or TLR9/MyD88 signaling and the IL-12 pathway." (PMID 36387171, 2022). "TLR9 promotes tumor regression by triggering a cytotoxic T cell (CTL) response and reducing the number of MDSCs, tumor-associated macrophages (TAMs), and Tregs." (PMID 36291769, 2022). "The combination of TLR9 agonists with the PD-1/PD-L1 blockade has shown an elevated number of multifunctional tumor antigen-specific T cells expressing TNF and IFNγ, and a proportion of memory precursor effector cells." (PMID 35745800, 2022). "MGN1703, which is DNA-based and essentially different from the CpG-ODN TLR9 agonist, has shown immune activation and anti-tumor efficacy in metastatic solid tumors." (PMID 35292881, 2022). "TLR9 promotes the maturation and migration of DCs from the tumor microenvironment to regional lymph nodes, where DCs activate tumor-specific cytotoxic T lymphocytes, leading to potent anti-tumor effects." (PMID 36359370, 2022). "In vivo and in vitro, TLR-9 signaling was found to repress miR-7 expression to strengthen the anti-tumor effect." (PMID 36499102, 2022). "In HCC, HMGB1 was proved to interact with mitochondrial DNA to promote the activation of toll-like receptor (TLR)-9 signaling in hypoxia condition for the stimulation of tumor development." (PMID 36267972, 2022). "Several preclinical studies have shown that TLR9 agonists can lead to anti-tumour effects in an NK- and CD8 T-cell-dependent manner." (PMID 36106115, 2022).
tumor (continued). "Antitumor response from Ad5D24-CpG treatment was determined to be highly reliant on TLR9-mediated NK cell activation, leading to the effective killing of tumor cells." (PMID 35740589, 2022). "In situ tumor vaccination with intratumoral injection of OX40 antibodies in combination with TLR3 or TLR9 agonists has been reported in rodent models to induce systemic antitumor immunity." (PMID 35055015, 2022). "Immune-mediated targeting of the tumor is likely a result of TLR9-medated T cell proliferation as well as maturation of APCs, following the TLR9 recognition of double-stranded adenoviral DNA." (PMID 35740589, 2022). "The property of TLR-9 to stimulate specific immune reactions by activating inflammation-like innate responses in immune cells makes TLR-9 a promising target in tumor therapy." (PMID 36230620, 2022). "As expected, the tumor burden and 7-week mortality were similar in global Tlr9–/– mice and FRC-Tlr9–/– mice between anti–PD-1 and ODN+anti–PD-1 treatments." (PMID 36278484, 2022). "Lately, TLR-9 agonists have drawn considerable attention at the frontier of research in melanoma immunotherapy since it alters the tumor microenvironment and enhances the anti-tumor immune response by elevating the expression of the TRL-9 receptor." (PMID 36499102, 2022). "Upon ligand recognition, TLR9 activation promotes downstream signaling, supporting either tumor progression or suppression, and therefore, can be used as a potential target in cancer therapy." (PMID 36611945, 2022). "We measured TLR9, 2 and 4 expressions in our tumor samples and classified our cohort of patients as showing high (≥2) or low (<2) score expression levels of TLR9 (n=22), TLR2 (n=28) and TLR4 (n=29)." (PMID 35990685, 2022). "A subsequent report argues that TLR9 is involved sensing tumor-derived DNA, DC maturation, and CTL priming." (PMID 35626062, 2022). "Ad5D24-CpG, an oncolytic adenovirus genetically manipulated to express TLR9 stimulating CpG islands, significantly controlled tumor growth compared to CpG unenhanced Ad5D24 treated tumors." (PMID 35740589, 2022). "The expressions and functions of miRNAs in immunotherapy employing tumor-infiltrating lymphocytes and Toll-like receptor 9 agonists are also discussed." (PMID 36499102, 2022). "Cytosine-phosphorothioate-guanine oligodeoxynucleotides (CpG ODNs) are toll-like receptor 9 (TLR9) agonists, and CpG ODNs are often used as anti-tumor adjuvants in clinical trials." (PMID 35748951, 2022). "CpG (cytosine-guanine oligodeoxynucleotide) is a TLR9 (toll-like receptor 9) agonist that stimulates anti-tumor immunity." (PMID 36146630, 2022). "Particularly in virus-induced gynecological cancers and cervical cancers, TLR9 promotes tumor regression by inducing cytotoxic T lymphocytes and reducing the number of MDSC, tumor-associated macrophages, and Tregs." (PMID 36365103, 2022). "On the one hand, TLR9 and its agonist CpG can have beneficial host effects and destroy tumor growth; on the other hand, they can promote tumor progression." (PMID 36611945, 2022). "Contrarily, it has been demonstrated that host TLR9 after sensing tumor cfDNA modulates the anti-tumor immunity in response to chemotherapy." (PMID 36359370, 2022). "The interaction between mtDNA and HMGB1 also reportedly plays an important role in tumor growth via TLR9 signaling." (PMID 35801206, 2022). "The stimulation of Toll-like receptor 9 (TLR9) on plasmacytoid DCs (pDCs) with CpG oligodeoxynucleotides (ODNs) can induce anti-tumor response in mouse models." (PMID 35681583, 2022). "Unmethylated cytidine-phosphate-guanosine (CpG) motifs (CpG ODNs), a TLR9 agonist, can stimulate antitumor immunity by activating the NF-κB pathway, and increase tumour cell death via cell cycle S phase arrest triggered by phosphorylated CHK2." (PMID 35801728, 2022).
tumor (continued). "Previous studies indicated that the combination of class A and class B CpG oligonucleotide antagonize tumor progression synergistically by activating distinct TLR9 signaling pathways." (PMID 35406387, 2022). "In liver cancer, hypoxia induces translocation of HMGB1 to cytosol and binds to mtDNA to activate TLR9 signaling pathway, which subsequently promotes tumor growth." (PMID 39871923, 2022). "The creation of new types of combined IGF1R, autophagy, and/or TLR9 signaling inhibitors would play a significant role in the development of more personalized anti-tumor therapies." (PMID 35651701, 2022). "Correspondingly, disruption of NETs or suppression of TLR9 inhibited tumor progression in preclinical models." (PMID 35747797, 2022). "Specifically, Toll-like Receptor 9 (TLR9) can detect DNA released by tumor cells following chemotherapy leading to enhanced antigen presentation and improved antitumor immune responses." (PMID 36387071, 2022). "TLR9 agonists lead to broad activation of immune cells, including APCs and T cells, and suppress Treg and MDSCs in tumor microenvironments." (PMID 36582243, 2022). "TLR2/TLR9 activation has also been shown to enhance DC maturation, which is essential for the effective processing and presentation of tumor antigens on MHC molecules." (PMID 35740589, 2022). "In line with this, there is evidence that cfDNA released by dead or dying tumor cells can activate TLR9 signaling, which in turn inhibits apoptosis and enhances autophagy, thereby promoting tumor growth." (PMID 36140548, 2022). "The PMA-trapped neoantigen vaccine was developed to codeliver tumor neoantigen and the Toll-like receptor 9 agonist CpG (NeoV), abbreviated as PMA-NeoV." (PMID 35217574, 2022). "Plasmacytoid DC usually promote the anti-tumor responses via the Toll-like receptor 9 (TLR9) -dependent synthesis of interferon-α (IFN-α), interleukin-6 (IL-6) and tumor necrosis factor-α (TNF-α)." (PMID 36143308, 2022). "Previous studies have shown that treatment with TLR9 agonists enhances anti–PD-1 therapy via altering the tumor immune microenvironment, particularly CD8+ T cell immunity." (PMID 36278484, 2022). "In tumor microenvironment, mtDNA released from necrotic tumor cells can be sensed by TLR9, which accelerates tumor recurrence after irradiation." (PMID 39871923, 2022). "It's worth noting that TLR1, TLR2, TLR3, TLR7, TLR8, and TLR9 were adversely connected with RNAss in the majority of cancers, but favourably correlated with RNAss in a very small number of tumours (KIRC, MESO, LAML, CHOL, KICH and THYM)." (PMID 35801728, 2022). "TLR9 level was higher in poorly differentiated tumors (G3), in extensive tumor dimensions (T3–T4) and in lesions with lymph nodes involvement (N3–N4) but these differences were not statistically significant." (PMID 34439137, 2021). "TLR9 is expressed in EAC tumors, and cytoplasmic TLR9 immunoreactivity correlates with high pathological tumor stage, positive lymph nodes, distant organ metastases, high tumor grade, tumor unresectability, and decreased 10-year survival rates." (PMID 34439930, 2021). "Exposure to extracellular cf‐rDNA molecules stimulates the survival of tumor cells, represses AIM2 expression, and reduces apoptosis, thereby facilitating tumor malignancy by triggering TLR9‐MyD88‐NF‐kB signaling." (PMID 34014039, 2021). "The rationale of these combination therapies is based on the enhanced TLR9 stimulation and tumor-specific CTLs activity carried out by cytotoxic treatments as well as immune checkpoint blockades in TME." (PMID 35056969, 2021). "Differently, TLR9 agonist, CpG ODN, potentiated tumor antigen presentation activity of TAMs, instead of M1-like polarization, causing slowed tumor growth in vivo when combined with engineered T cell transfer." (PMID 33990205, 2021). "TLR9 level was higher in poorly-differentiated tumors (G3), in tumor of larger dimensions (T3-T4) and with lymph nodes involvement (N3-N4) but without statistical significance." (PMID 34439137, 2021).
tumor (continued). "Unmethylated CpG ODN1826, a TLR9 agonist, has been shown to affect tumor growth in TC-1- and TC-1/A9-induced tumors and has also been demonstrated to be an effective adjuvant for DNA immunization in the TC-1 tumor model." (PMID 34205330, 2021). "CpG as the TLR9 agonist has been reported to activate tumor-specific CD8+ T cells or modulate the tumor microenvironment by down-regulating Treg or MDSC levels." (PMID 34611173, 2021). "Unmethylated CpG-containing oligodeoxynucleotides are strong TLR agonists (TLR9) and activators of anti-tumor immunity and of dendritic cell function." (PMID 33503958, 2021). "Collectively, the results corroborated the previous finding that systemic tumor elimination by TLR9 agonists was partially CD4+ T cell-dependent." (PMID 35008305, 2021). "CxCa tumor cells too have downregulated TLR9—a consequence of HPV16 E6 and E7 mediated inhibition of the TLR9 promoter." (PMID 33996630, 2021). "Using synergistic models, it was documented that agonist-mediated activation of TLR-9 either alone or in combinatorial approaches with chemotherapeutic and targeted therapeutic results in amelioration of tumor growth." (PMID 34202080, 2021). "At the same time, activated TLR9 signaling in tumor cells not only falls short of inducing an antitumor immune response, but even facilitates HCC survival." (PMID 34025657, 2021). "The treatment of CAL-1 cells with tumor supernatant or combination of TGFβ and TNFα prevented TLR9-induced production of type I IFNs." (PMID 33919546, 2021). "CMP-001 is a type A CpG packaged with a virus-like particle that activates tumor-associated plasmacytoid dendritic cells via TLR9 inducing type I IFN and anti-tumor CD8+ T cells." (PMID 34178657, 2021). "DLBCL-derived IL-8 interacted with its receptor on neutrophils to form NETs, resulting in upregulation of the Toll-like receptor 9 and its downstream signaling pathway to promote tumor progression." (PMID 34458135, 2021). "In response to chemotherapy, TLR9 acts as a tumor sensor by recognizing tumor released DNA, triggering an immune response and activating tumor-specific cytotoxic T lymphocytes (CTLs)." (PMID 33804856, 2021). "The anti-tumor effect of TLR9 signals is derived from the enhanced secretion of type-1 IFN, including IFNa from pDCs through TLR9 activation." (PMID 34573939, 2021). "In animal models, TLR9 stimulation triggers the break of tumor tolerance and induces immunity against AML and ALL." (PMID 34149402, 2021). "The effective anti-tumor immune response induced by synthetic CpG-ODN agonists of TLR9 in preclinic and clinical studies with anti-PD-1 antibody therapy revealed the critical role IFN-γ signaling for anti-PD-1 response." (PMID 34282215, 2021). "Herein, we decided to investigate the role of four different MyD88-dependent single TLRs (TLR2−/−, TLR4−/−, TLR7−/− and TLR9−/−) in BCG tumor treatment." (PMID 34341449, 2021). "pDCs are able to elicit an anti-tumor response by secreting high levels interferon-α (IFN-α) upon triggering of the Toll-like receptor 9 (TLR9)." (PMID 32602047, 2020). "To determine the effects of TLR9 activation on immune system, we used flow cytometry to analyze the immune cells from spleen and tumor after ODN1585 treatment." (PMID 32483468, 2020). "Specifically, approximately 44.44% of the tumor samples with high TLR9 expression showed strong PD-L1 staining, and 75.47% of those with low TLR9 expression showed weak PD-L1 staining or no PD-L1 staining (p < 0.001)." (PMID 32483468, 2020). "One of the possible approaches is the therapeutic activation of tumor-associated pDCs using TLR7 and TLR9 agonists." (PMID 32054102, 2020). "Altogether, these results indicate that the activation of TLR7, TLR8, and TLR9 of TAMs can change macrophages from a tumor-promoting effect to an anti-tumor effect." (PMID 33224886, 2020). "Antitumor effects of TLR9-targeted therapies have been described in animal models against various tumor types, including melanoma." (PMID 32054102, 2020).